CCNB1 (cyclin B1)
Diseases named in the same sentence as CCNB1 in open-access papers (continued):
Sharing a sentence is not in itself a finding about the gene and the disease.
pterygium (1 paper, 2020). A wedge-shaped fibrovascular lesion arising from the bulbar conjunctiva and extending to the cornea. "We presume that the LINC00472 network might function in pterygium via the FOXM1 PATHWAY, especially through the regulation of CCNB1, MYC, ERBB4, RELN, RB1, and CDH2 in the ceRNA network." (PMID 33299863, 2020). "There are 6 genes that are highly expressed in pterygium, MYC, CDH2, CCNB1, RELN, RB1, and ERBB4." (PMID 33299863, 2020).
sarcoidosis (1 paper, 2022). Sarcoidosis is a multisystemic disorder of unknown cause characterized by the formation of immune granulomas in involved organs. "Some dysregulated genes discovered in our meta-analysis have not been found to be associated with sarcoidosis previously, but variations of these genes such as CCNB1, BLOC1S1, and KIF1B are associated to some extent with fibrotic diseases, including complication of sarcoidosis and tuberculosis." (PMID 36203777, 2022).
scrapie (1 paper, 2020). A fatal disease of the nervous system in sheep and goats, characterized by pruritus, debility, and locomotor incoordination. "In addition, the brains of scrapie-affected hamsters show evidence of cell cycle activity with an increase in the proteins polo-like kinase (PLK) 1 and cyclin B1, and a decrease in PLK3 and Cdc25C." (PMID 32108870, 2020).
selenium deficiency (1 paper, 2022). A nutritional deficiency disease resulting from inadequate selenium levels in the body, which can lead to impaired function of selenoproteins essential for antioxidant defense and thyroid hormone metabolism. "This evidence combined with T-2 toxin resulting in decreased expression of CCNG1 mRNA suggests that selenium deficiency and T-2 toxin exposure could cause and accelerate chondrocyte apoptosis and necrosis in KBD cartilage partly through regulating CCNB1 and CCNG1." (PMID 36588792, 2022).
seminoma (1 paper, 2025). A radiosensitive malignant germ cell tumor found in the testis (especially undescended), and extragonadal sites (anterior mediastinum and pineal gland).
testicular germ cell tumor (1 paper, 2025). A germ cell tumor arising from the testis. "It has been shown that the aberrant development of PGCs and testicular germ cell tumors can result from the disruption in CCNB1 and CCNB2 genes." (PMID 41009526, 2025).
tongue tumors (1 paper, 2024). "Previous studies suggest that CDK1, CCNA2, and CCNB1 may be associated with inflammation, immune system disorders, and tongue tumors." (PMID 39553152, 2024).
Tuberous Sclerosis Complex (1 paper, 2022). "This adds to our body of information about the residues within Tuberin responsible for regulating the cytoplasmic retention of Cyclin B1 and supports the phenotypic data seen in the clinic with Tuberous Sclerosis Complex patients harbouring similar large deletions in Tuberin." (PMID 35947627, 2022).
urothelial carcinoma (1 paper, 2025). A malignant neoplasm derived from the transitional epithelium of the urinary tract (urinary bladder, ureter, urethra, or renal pelvis). "Furthermore, the SLC14A1 gene is also considered a novel tumor suppressor for urothelial carcinoma, and in PCa, the downregulation of its expression promotes tumor progression by activating the CDK1/CCNB1 and mTOR pathways and is closely associated with biochemical recurrence (BCR) of PCa." (PMID 40260298, 2025).
uterine serous carcinoma (1 paper, 2024). "Additionally, in uterine serous carcinoma, UCHL1 interacts with cyclin B1, which is essential for mitosis during tumor cell cycle progression." (PMID 38727276, 2024).
vulvar cancer (1 paper, 2015). "However, to our knowledge no previous study has investigated Cyclin B1 and CDK1 in vulvar cancer." (PMID 25849598, 2015).
vulvar squamous cell carcinoma (1 paper, 2015). An invasive squamous cell carcinoma arising from the vulva. "Therefore, we evaluated the statuses of CDK1Tyr15, pCDK1Thr161, Cyclin B1 (total) and pCyclin B1Ser126 in 297 cases of vulvar squamous cell carcinomas by immunohistochemistry." (PMID 25849598, 2015). "In conclusion, CDK1Tyr15, pCDK1Thr161, Cyclin B1 (total) and pCyclin B1Ser126 may be involved in progression of vulvar squamous cell carcinoma." (PMID 25849598, 2015).
Wilms tumor (1 paper, 2023). An embryonal neoplasm characterized by the presence of epithelial, mesenchymal, and blastema components. "In conclusion, our findings imply that CCNB1 is a significant prognostic biomarker and a possible therapeutic target for Wilms tumor." (PMID 37592341, 2023).
tumor (498 papers, 2002 to 2026). "Elevated levels of CCNB1 are associated with tumor cell immortality and chromosomal instability, leading to tumor cell invasion and poor prognosis in cancer patients." (PMID 41568058, 2026). "To investigate the molecular mechanisms underlying CCNB1’s role in tumor progression, we examined its PPI network, analyzed genes associated with CCNB1, and conducted enrichment analysis." (PMID 38581717, 2024). "While CDC20 appears to be more closely associated with tumor grade, CCNB1 is more strongly associated with tumor stage and survival outcomes." (PMID 39795587, 2024). "Research has shown that CCNB1 is significantly overexpressed in a range of human tumors and is associated with tumor cell proliferation, metastasis, and poor outcomes." (PMID 39456780, 2024). "As highlighted earlier, CCNB1 upregulation has been linked to tumor progression in several cancer types." (PMID 38581717, 2024). "The results of our study exhibited a significant association between the expression of CCNB1 and age, residual tumor status, T stage, N stage, and Gleason score." (PMID 39318781, 2024). "CCNB1 also called cyclin B1, has shown that is closely associated with tumor progression and was highly expressed in tumor tissues or cells." (PMID 37407632, 2023). "These disparities indicate that more research is warranted to elucidate the underlying mechanism and function of CCNB1 in tumour development and prognosis in various tumour types." (PMID 36418517, 2023). "Cell proliferation–related genes, including Mki67, Cdk1, Plk1, and Ccnb1, were downregulated in tumor-infiltrating SENP7-deficient CD8+ T cells." (PMID 35143421, 2022). "Then, we analyzed the expression of CCNB1 in normal breast tissue and BC tissue, and the correlation of CCNB1 with tumor mutation burden (TMB), methylated, and immune cell infiltration in BC." (PMID 36040381, 2022). "For instance, it was found that the degree of CCNB1 expression was clinically linked with a number of clinicopathological characteristics, such as gender, smoking status, tumor stage, and tumor stage." (PMID 36225197, 2022). "The correlation heatmap showed that YTHDF1 H-score was positively associated with cyclin B1 H-score (R = 0.25, p = 0.03) and tumor size (R = 0.38, p = 0.001)." (PMID 34359836, 2021). "TTP mainly functions as a tumor suppressor by targeting mRNAs encoding proteins related to the cell cycle (Cyclin B1 and D1), cell death and proliferation (Bcl-2 and cIAP), angiogenesis (VEGF), and EMT (Snail, Twist1, ZEB1, SOX9, MACC1, MMP2, MMP9, and IL-6)." (PMID 32967226, 2020). "Exonic deletions were detected in the PPP2R5A, FHIT, LRP1B, and OPCML tumor suppressor genes, as well as in genes implicated in cellular proliferation (CCNB1, ANAPC5, PIK3C2A) and DNA repair (SMARCA5)." (PMID 30836646, 2019). "It has been reported that both cyclin D1 and cyclin B1 accelerate the cell cycle and are associated with malignance and proliferation of tumor cells 60-63." (PMID 31523191, 2019). "Silencing of cyclin B1 in tumor cells increases susceptibility to taxol and leads to growth arrest in vivo." (PMID 28008150, 2017). "These discrepancies suggest that further studies are warranted to elucidate the underling mechanism and role of cyclin B1 in pathogenesis and prognostic value in different tumor types." (PMID 27903976, 2017). "The results indicated significant association between positive/high cyclin B1 expression and Size of tumor (OR 0.60, 95% CI 0.38, 0.93; P = 0.02) and Distant metastasis (OR 0.30, 95% CI 0.13, 0.71; P = 0.006), using fixed-effect models." (PMID 29221213, 2017). "High levels of nuclear cyclin B1 are associated with high tumor grade, larger tumor size and higher metastasis probability, therefore a high level of cyclin B1 is considered a predictor of poor prognosis." (PMID 26517518, 2015).
tumor (continued). "We found that in VSCC high expression of Cyclin B1 (total) was significantly associated with malignant features, including large tumor diameter, poor histological differentiation and deep invasion." (PMID 25849598, 2015). "That is, short-term overexpression of miR-744 can induce Cyclin B1 (Ccnb1) expression and enhance cell proliferation, while prolonged expression caused chromosomal instability and in vivo tumor suppression." (PMID 25961434, 2015). "High MAI, PPH3, cyclin B1, Ki67, and cyclin A were significantly associated with younger age, larger tumour size, ER-negativity, HER2-positivity, and high grade (data not shown)." (PMID 24324728, 2013). "We also assessed the expression of other NF-κB–regulated genes Bcl-2, Bax and Cyclin B1, the overexpression of which have been linked to tumor survival, apoptosis and cell cycle arrest." (PMID 21901145, 2011). "Cyclin A/Cdk2 (CCNA2) and CCNB1 are present in many tumours and some were previously associated with poor prognosis and in metastasis." (PMID 19753302, 2009). "With tumour size and nodal status, cyclin B1 was the only factor independently associated with poor MFS (RR 2.31, 95% CI 1.17–4.59, P=0.016) and OS (RR 1.79, 95% CI 1.28–4.14, P=0.04)." (PMID 19293801, 2009). "Notably, CCNB1 (Cyclin B1) is a pivotal regulator of the cell cycle, and its aberrant expression has been associated with increased tumor invasiveness." (PMID 41333208, 2025). "Overexpression of CCNB1 has been linked to increased cell proliferation and tumor growth in PCa54." (PMID 41402347, 2025). "By contrast, luminal cluster 2 was enriched in a proliferative gene signature (Mki67, Ccnb2, Cdk1, Ccnb1 and Ccnd1), which may be associated with cycling progenitors fuelling tumour growth." (PMID 38238426, 2024). "Taken together, these results suggest that the favorable prognosis associated with low CCNB1 expression may be partially attributed to anti-tumor immune activity." (PMID 37592341, 2023). "Clinical correlation showed that the expression of CCNB1 was significantly associated with the pathological type and tumour progression, suggesting that the gene may be involved in the malignant progression of WT." (PMID 37592341, 2023). "According to the results of the study, CCNB1 was highly expressed in tumor tissues and was associated with a poor prognosis; therefore, we hypothesized that CCNB1 might be an oncogene." (PMID 37758792, 2023). "First, it explains the heterogeneity observed in tumor A3B protein expression by IHC, with strong positivity associating with active cell cycling and specifically with the G2/M phase of the cell cycle (coincident with Cyclin B1 positivity)." (PMID 37190094, 2023). "One study found that CCNB1 caused T cell-dependent antibody responses in patients with cancer and precancerous lesions, suggesting that this gene is an important player in the immune control of tumour growth." (PMID 37592341, 2023). "Moreover, in hepatic cell cancer (HCC), expression of Ccnb1 and Tpx2 was positively associated with higher immune cell infiltration in tumours, suggesting potential immune-regulatory roles for the proteins." (PMID 36010935, 2022). "However, low levels of LIMA1 are associated with tumor growth, and LIMA1 binds to the known miR-142 target RAC1 while low levels of Cyclin B1 (CCNB1) are associated with reduced cell growth in accordance with a tumor-suppressive role of miR-142." (PMID 36291816, 2022).
tumor (continued). "Indeed, not only is abnormal cyclin B1 expression associated with tumorigenesis, evidence for a link between the mitochondrial fragmentation phenotype and promotion of tumor growth is also increasing." (PMID 33495511, 2021). "Meanwhile, the cyclin B1 H-score was positively associated with tumor size (R = 0.24, p = 0.046)." (PMID 34359836, 2021). "We next tested whether overexpression of cyclin B1 attenuates the survival of BRCA1-associated tumor cells." (PMID 30327455, 2018). "On the other hand, intratumoral injection of cyclin-B1-siRNA (1 μg and 5 μg) complexes with MPG-8/chol-MPG-8 at a 1/20 molar ratio and cyclin-B1 siRNA with MPG (5 μg) caused 75% reduction of tumor volume for 1 μg and complete disappearance of tumor for 5 μg of Cyclin-B1-directed siRNA." (PMID 29861465, 2018). "Expression of proliferative markers like Ki67 and cyclin B1 is higher in luminal B tumours than in luminal A. Tumours of this subgroup are associated with an unfavourable prognosis than in luminal A-type and may benefit from the chemotherapy." (PMID 27884978, 2016). "Whether these changes are associated with tumor recurrence, particularly in African American men, whose immunity to cyclin B1 might be associated with increased tumor aggressiveness, remains to be determined." (PMID 24860838, 2014). "Long-term overexpression of miR-744 may cause chromosomal instability and inhibit tumor growth by prolonging activation of Ccnb1 in mouse." (PMID 24991193, 2014). "The lower growth of L50 tumours was associated with a strong reduction in cyclin B1." (PMID 22107808, 2011). "Several studies have shown that serum AAbs to cyclin B1 protein can be found in patients with various tumors and might be a useful diagnostic marker in combination with AAbs against several other tumor antigens." (PMID 21113302, 2010). "Furthermore, immunohistochemically detected expression of cyclin B1 showed a significant association with tumour grade, Ki-67 and Her-2/neu as well as with cyclin E expression." (PMID 19615042, 2009). "Indeed, cyclin B1 represents a protein antigen whose function as a tumor antigen is associated with increased cytoplasmic accumulation followed by degradation through ubiquitination." (PMID 17129372, 2006). "Consequently, CCNB1 is likely implicated in tumor progression." (PMID 38581717, 2024). "DNA hypomethylation and gene mutation of CCNB1 may contribute to oncogenesis and tumor progression." (PMID 38581717, 2024). "We investigated the expression levels of circ_0043256, circ_0004789, miR-28–5p, miR-5683, and CCNB1 in 32 paired GC and non-tumor margin tissues by RT-qPCR." (PMID 41568058, 2026). "IL-6 and B-cell lymphoma 2 showed downregulated expression in tumor tissues, while cyclin-dependent kinase 1, cyclin-dependent kinase 2, cyclin B1, Erb-B2 receptor tyrosine kinase 2, and cyclin B2 were upregulated." (PMID 41650055, 2026). "We studied 32 paired tumor and adjacent tissues to assess all genes and CCNB1 protein expression, along with correlations, histopathological associations, ROC curves, and survival outcomes." (PMID 41568058, 2026). "The SNRPB overexpression group exhibited significantly heavier tumors, while CCNB1 knockdown led to a reduction in tumor weight." (PMID 40682115, 2025).